LCT (lactase)
Diseases named in the same sentence as LCT in open-access papers (continued):
Sharing a sentence is not in itself a finding about the gene and the disease.
lactose intolerance (continued). "Furthermore, primary late onset lactose intolerance is characterized by a gradual reduction in lactase activity, and it generally manifests itself only after the age of 5 to 6 years of age in white populations, although it can occur earlier in predominantly non-white populations." (PMID 34579138, 2021). "The author assumes that in the future, the proposed solution may also contribute to provide an alternative diagnostic assay for lactose intolerance resulting from a lack of β-galactosidase (lactase) in the body." (PMID 30308030, 2018). "Transient lactose intolerance, due to loss of intestinal brush border lactase, also complicates SAM, thus milk based feeds may not be optimal for nutritional rehabilitation." (PMID 30345381, 2018). "One application could be the confinement of lactase to address lactose intolerance." (PMID 25016923, 2014). "Furthermore, during severe diarrhea, the intestinal epithelium might get damaged and lead to (secondary) lactose intolerance, as lactase expression in the small intestine is confined to the enterocytes’ villi." (PMID 25255831, 2014). "The increase in diagnosed cases of lactose intolerance can also be linked to advancements in diagnostic methods, such as the hydrogen breath test, which measures hydrogen production after lactose ingestion, and genetic tests that identify polymorphisms associated with lactase non-persistence." (PMID 39202720, 2024). "Additionally, gradual adaptation to lactose may occur in some cases of primary lactose intolerance because some beneficial bacteria in the gut that secrete lactase slowly increase under certain conditions when lactose-containing foods are progressively introduced into the diet." (PMID 39605839, 2024). "Unlike adult-onset lactose intolerance, congenital lactose intolerance is caused by rare homozygous or complex heterozygous mutations within the LCT gene, which encodes lactase." (PMID 41502574, 2025). "The term “classic lactose intolerance” was traditionally used for symptoms that appear after consuming a large amount of lactose but should not be confused with lactase digestion disorder, as intolerance does not always lead to a digestion disorder." (PMID 41471052, 2025). "For treating lactose intolerance, the neonatologists primarily opted for exogenous lactase rather than lactose-free formula milk." (PMID 39201948, 2024). "People who suffer from lactose intolerance experience stomach problems when they drink milk or consume milk products because they do not produce enough lactase amount in their small intestines to digest the milk sugar, which is lactose." (PMID 39796443, 2024). "This, in turn, implies that while there is an increased prevalence of lactose intolerance in infants born earlier, oral treatment with lactase is equally effective regardless of gestational age." (PMID 39201943, 2024). "Lactose intolerance depends on the absence of a gene named LCT, which provides instructions to produce an enzyme called lactase, which helps to digest lactose." (PMID 39339708, 2024). "It was not feasible to establish a control group consisting of individuals with lactose intolerance who were not administered lactase treatment, as it would be unethical to diagnose the condition and then withhold treatment." (PMID 39201943, 2024). "People with lactose intolerance have stomach problems when they drink milk or eat milk products because they do not have enough lactase activity in their small intestines to digest the milk sugar lactose." (PMID 38481973, 2024). "Since the absence of lactase from the mucosal surface and, subsequently, lactose intolerance is anthropologically “normal”, the persistence of lactase and lactose tolerance has developed through mutations." (PMID 37371306, 2023). "In some adults without lactase persistence drinking milk produces unpleasant abdominal symptoms, a condition termed lactose intolerance." (PMID 36757941, 2023).
lactose intolerance (continued). "We did not stratify subjects based on age, gender or race because evidence suggests that lactose intolerance does not depend on demographics but on the dose and differences in the lactase non-persistent gene." (PMID 36839159, 2023). "Lactase relieved lactose intolerance–related symptoms better than Bi-07 in Booster Alpha but not Booster Omega." (PMID 36149331, 2022). "Two crossover clinical trials, Booster Alpha and Booster Omega, were performed in participants with lactose intolerance, where 2 × 1012 CFUs Bi-07, 4662 FCC lactase, or placebo was consumed simultaneously with a lactose challenge, with 1-wk washouts between challenges." (PMID 36149331, 2022). "To ensure that any effects of the lactose intolerance test or lactase administration during visit 1 did not affect the results at visit 2, we set a gap of 1 week between the two visits." (PMID 33490624, 2021). "The term HIT is used in a similar manner as the concept of lactose intolerance (which occurs due to a lack of the lactase enzyme), since it is presumed that the HIT symptoms are related to a lack or diminished activity of the enzyme DAO." (PMID 34209583, 2021). "We observed a non-significant 8% higher risk of mortality among participants with the TT/TC genotype compared to the lactase non-persistence CC genotype (i.e., lactose intolerance)." (PMID 34901125, 2021). "CC genotype carriers (lactase non-persistence, i.e., lactose intolerance) had approximately 27% lower reported consumption of non-fermented milk than CT and TT carriers (222 vs. 279 and 283 g/day)." (PMID 34901125, 2021). "Lactose intolerance (LI) occurs when the small intestine does not produce enough of the lactase enzyme to digest lactose, the sugar found in milk." (PMID 32590986, 2020). "Lactose intolerance is a clinical syndrome diagnosed by adverse reactions due to ingestion of lactose; it is not necessarily related to low lactase activity level or having low lactase activity by our standards." (PMID 33036568, 2020). "They provided guidelines, which emphasize that it is important to consider lactose intolerance in the diagnostic work-up of patients with suspected IBS, especially in individuals of ethnic backgrounds with higher incidence of lactase non-persistence." (PMID 31505870, 2019). "Lactase non-persistence (leading to primary lactose intolerance) is a geneticallydependent inability to digest lactose in adulthood." (PMID 28497837, 2017). "Lactose intolerance develops primarily due to the absence of the enzyme lactase and treatment involves avoidance of lactose-containing foods or ingestion of commercially available lactase enzyme preparations prior to their consumption." (PMID 27999602, 2016). "Symptoms of lactose intolerance generally do not occur until there is less than 50% of lactase activity." (PMID 26393648, 2015). "Then, different types of lactose intolerance are discussed, and the molecular aspects of lactase persistence/non-persistence phenotypes are investigated." (PMID 26343715, 2015). "Patients with lactose intolerance responded immediately to oral lactase therapy and discontinued the enzyme after 6 months without recurrence." (PMID 22988522, 2012). "Lactase non-persistence (adult-type hypolactasia, "lactose intolerance") is a genetically determined normal trait where down-regulation of lactase activity occurs during childhood." (PMID 21235777, 2011). "Lactase non-persistence, often called lactose intolerance, is the normal condition where lactase activity in the intestinal wall declines after weaning." (PMID 21235777, 2011). "Many individuals suffer from symptoms of lactose intolerance but did not have documented lactose maldigestion or the intolerant ones may carry the lactase persistence gene." (PMID 37585412, 2023).
lactose intolerance (continued). "Researchers studying the evolution of lactase persistence consistently take the view that selection pressures are mediated through lactose intolerance, meaning that the key issue is that lactase persistent individuals are able to consume milk without adverse consequences." (PMID 36757941, 2023). "The report of this study wrongly conflated the two concepts by referring to “lactase non-persistence (lactose intolerance)” as if they were equivalent whereas in fact, as Evershed and colleagues point out, most LNP individuals are not lactose intolerant and can drink milk without problems." (PMID 36757941, 2023). "Symptoms of lactose intolerance generally do not occur until lactase activity falls below 50%." (PMID 36296945, 2022). "The reasons for a pathological reaction to milk in patients with MS could be many: on the one hand, the lack of lactase could explain the lactose intolerance followed by cross-reactions to the components of milk." (PMID 35807891, 2022). "Lactase non-persistent adults may develop symptoms of lactose intolerance when consuming dairy products." (PMID 34630506, 2021). "Alternatively, lactase enzymes could be ingested to enjoy the benefits of milk without experiencing symptoms of lactose intolerance." (PMID 33919083, 2021). "Individuals with lactase non-persistence and infrequent consumption of dairy may develop lactose intolerance." (PMID 31505870, 2019). "The high incidence of lactose intolerance and lactase nonpersistence, as well as varying cultural preferences among ethnic minorities, may play a role in the lower consumption of dairy among such groups." (PMID 31430962, 2019). "The exact incidence of lactose intolerance is unknown, but according to some estimates the relative or absolute absence of lactase occurs in 70% of the world's population, particularly in Asia, Africa, and South America." (PMID 31041447, 2019). "Lactose intolerance may be present in IBD patients, but it may still be possible to consume dairy produce with lower lactose content, such as cottage cheese and butter as also yoghurt, because of live cultures that produce their own lactase." (PMID 30209778, 2018). "Although lactose intolerance may be present in IBD patients, it may still be possible for patients to consume dairy produce with lower lactose content, such as cottage cheese and butter as also yoghurt, because of live cultures that produce their own lactase." (PMID 30209778, 2018). "Furthermore, the study design used symptomology rather than genotype to diagnose lactose intolerance, so it is also not clear as to what percentage of individuals in this study were genetically considered lactase non-persistent." (PMID 28684688, 2017). "Individuals who have genotypic lactase non-persistence (lactose intolerance) consume on average less milk products than those who carry the lactase persistent alleles as they produce less lactase resulting in GI upset when lactose is consumed in higher amounts." (PMID 27469612, 2017). "Basically, overall, few individuals are achieving the recommended servings of dairy (>3 servings or ≥1.3 servings/1000-kcal), with some groups further avoiding consumption either due to lactase non-persistence/lactose intolerance (which may be perceived or clinical) or due to cultural influences." (PMID 31405126, 2019). "In contrast, individuals with lactase non-persistence experience a decrease in LCT gene expression and lactase enzyme production as they age, leading to lactose intolerance." (PMID 37447285, 2023). "The genetic basis of Lactase persistence (LP) or Non-persistance (LNP) is now well known, so genetic testing is becoming more and more used to obtain a better diagnosis of lactose intolerance and its clinical value increases with age, being maximal in adulthood." (PMID 34515921, 2021).
inflammatory bowel disease (10 papers, 2010 to 2025). A spectrum of small and large bowel inflammatory diseases of unknown etiology. "Additionally, in individuals with lactase persistence the occurrence of gastrointestinal infection, inflammatory bowel disease, abdominal surgery and other health issues can also cause a decrease in lactase activity (secondary lactase deficiency)." (PMID 26393648, 2015). "However, the inclusion of this clinical population in future research may provide further insights into the potential association between lactase persistence and inflammatory bowel disease." (PMID 21167073, 2010). "Additionally, a secondary or temporary lactase deficiency may arise as a result of acute intestinal infections, such as viral gastroenteritis, or from chronic conditions like untreated coeliac disease or inflammatory bowel disease, where damage to the intestinal mucosa impairs lactase expression." (PMID 41011418, 2025). "As associations between MAP and inflammatory bowel disease have largely been limited to individuals with CD, this study did not evaluate lactase persistence in the ulcerative colitis context." (PMID 21167073, 2010).
malaria (9 papers, 2009 to 2025). Malaria is a serious and sometimes fatal disease caused by a parasite that commonly infects a certain type of mosquito which feeds on humans. "Fulani are a widely spread African ethnic group characterized by lower susceptibility to Plasmodium falciparum, clinical malaria morbidity and higher rate of lactase persistence compared to sympatric tribes." (PMID 21235777, 2011). "These include examples such as lactase persistence mutations near LCT (0.01–0.15) and malaria resistance mutations affecting DARC (0.08) and HBB (0.1)." (PMID 34528508, 2021). "During the last 10,000 years protection against malaria and lactase persistence have been two of the strongest selection forces shaping the human genome." (PMID 21235777, 2011). "Many well-characterized human genes that play important roles in environmental adaptation have been identified, such as HBB (Hemoglobin-B), which causes resistance to malaria, and LCT (lactase), which is essential for the digestion of dairy products." (PMID 21386899, 2011). "Lactase persistence in certain populations affects the availability of fatty acids which will affect drug absorption, and malaria has an extensive impact on the gastrointestinal system, which could inhibit digestion and limit fatty acid availability." (PMID 39905737, 2025). "Some examples in humans include malaria resistance and lactase persistence." (PMID 19742321, 2009). "Asymptomatic parasitaemia was used as the main phenotype, assessment of the suggested protective effects of lactase persistence on clinical malaria episodes, severe malaria or malaria mortality was not applicable." (PMID 21235777, 2011). "In the 1990s it was suggested that lactase non-persistence would have been selected by malaria, like beta-thalassaemia and glucose 6-phosphate dehydrogenase deficiency." (PMID 21235777, 2011). "Among the Fulani with lactase non-persistence CC genotypes at the C/T-13910 locus, 24% had malaria parasites detectable by microscopy compared to 18% for lactase persistent genotypes (P = 0.29)." (PMID 21235777, 2011).
Obesity (9 papers, 2012 to 2025). Accumulation of substantial excess body fat. "A strong association of lactase persistence (LP) with BMI and obesity has also been traced in a Spanish Mediterranean population." (PMID 22937140, 2012). "He found a positive association of lactase persistence with BMI and overweight and obesity." (PMID 34718860, 2022). "In addition, the lactase (LCT) gene was shown to be associated with risk to obesity only in individuals who had high milk consumption." (PMID 24392269, 2012). "Obesity has very weak relationship with latitude, but both diseases follow adult lactase distributions colliding in this plane." (PMID 31452062, 2020). "Mendelian randomization studies using the lactase persistence gene might also be helpful in teasing out the unconfounded effect of milk consumption on obesity." (PMID 23593300, 2013). "The proportion of non-lactase persistent participants with obesity was higher than in lactase persistent participants, and the proportion of lactase persistent participants with a normal weight was higher than among non-lactase persistent." (PMID 39891239, 2025). "Although the sample size of the Danish study represented 64% and 95% of the pooled sample sizes for BMI and overweight-obesity (respectively), its actual weight in the meta-analysis is lower due to the very low prevalence of lactase non-persistence in this study." (PMID 27170764, 2016).
celiac disease (8 papers, 2013 to 2025). An autoimmune genetic disorder with an unknown pattern of inheritance that primarily affects the digestive tract. "Poor intestinal absorption and secretion also have been associated with a variety of different human diseases, such as coeliac disease, lactase deficiency, or Whipple’s disease." (PMID 34228720, 2021). "In cases of cow’s milk enteropathy or celiac disease with villous damage, lactase concentrations are typically reduced while sucrase levels are sufficient." (PMID 29270244, 2017). "Forty-nine patients with suspected carbohydrate intolerance underwent genetic testing for lactase non-persistence, hereditary fructose intolerance, and celiac disease risk." (PMID 39203877, 2024). "Some causes of malabsorption are directly related to genetic markers of hereditary intestinal alterations, such as the non-persistent lactase genotypes in primary lactose, but also indirect genetic predisposition related to the HLA-DQ2/8 haplotypes in celiac disease." (PMID 39203877, 2024).